CDX2 (caudal type homeobox 2)
Diseases named in the same sentence as CDX2 in open-access papers (continued):
Sharing a sentence is not in itself a finding about the gene and the disease.
tumor (continued). "In this present study, we have investigated CDX2 as a potential candidate gene for sporadic CRC by a thorough search of all exons and exon/intron boundaries for DNA polymorphisms and rare variants in a panel of CRC tumours." (PMID 11161380, 2001). "Similarly, low CDX2 was more frequent in advanced tumor stage pT4 compared to pT1–T3 (p = 0.002)." (PMID 41388313, 2025). "However, it is crucial to acknowledge that distinct regions within a tumor may exhibit varying intensities of CDX2 staining, potentially exerting a profound impact on prognosis and therapeutic outcomes." (PMID 38786321, 2024). "In summary, our study highlights the role of developmental and lineage-restricted transcription factors, such as Cdx2, in maintaining tissue-location-specific transcriptional programs that differentially regulate stemness and differentiation, and are critical dependencies for tumor development." (PMID 38360902, 2024). "CC tumors with absent/low levels of CDX2 expression and a low percentage of positive tumor cells (< 25.0%) were associated with CDX2 hypermethylation (p = 0.044 and p = 0.048, respectively) and were preferentially of mesenchymal type and hMLH1/hPMS2 defective tumors (p < 0.005)." (PMID 38093305, 2023). "Our findings suggested that CDX2 may be a potential biomarker for tumor immunotherapy response." (PMID 36277982, 2022). "Also, CDX2 and Ki67 expressions were compared between tumor organoids and patient tumor sections." (PMID 35721501, 2022). "Hence, we attempted to validate the involvement of CDX2 in FXR-mediated tumor inhibition in CRC." (PMID 35449124, 2022). "This may be explained by several studies showing the tumor-suppressive role of CDX2 protein." (PMID 35463729, 2022). "Furthermore, CRC with advanced tumor stage and high tumor grade lost the CDX2 expression." (PMID 33058307, 2021). "Therefore, we performed gene expression analysis of Paneth cell markers in our Cdx2-ERT2Cre;Apcfl/fl;Atg5fl/fl cohort and found no changes in Paneth cells with loss of autophagy in either tumor or matched normal tissue." (PMID 34138755, 2021). "Conversely, several studies have indicated that CDX2 may act as a tumor suppressor." (PMID 33639844, 2021). "E-cadherin is an intercellular adhesion protein fulfilling a prominent role in epithelial differentiation, which implies CDX2 may play a role in CRC metastatic progression while maintaining the tumor’s differentiation status through the induction of E-cadherin." (PMID 33755595, 2021). "Interestingly, Sample_15, a Gleason pattern 4 tumour, shows high enrichment for FOXA1, HOXB13 and CDX2, followed by Fra1/2, Atf3, JunB and AP-1 binding sites enriched in Gleason pattern 3 tumours, suggesting a transitionary state between the two regulatory states." (PMID 34911933, 2021). "It has also been hypothesized that CDX2 has a tumour suppressor role in the adult colon." (PMID 34940086, 2021). "However, the pathological role of CDX2 remains controversial, and inconsistencies may be related to tumor location and type." (PMID 33621200, 2021). "To elucidate how CDX2 may promote tumor growth at the metastatic site, we evaluated certain EMT markers in CDX2 knockdown CRC cells because some evidence suggests mesenchymal-epithelial transition (MET) is essential for metastatic tumor colonization in the liver." (PMID 33755595, 2021). "Furthermore, viable tumor areas were scored as being poorly, moderately, and/or well differentiated in a blinded fashion by a pathologist, revealing statistically significant differences between control and CDX2 knockdown xenograft tumors." (PMID 33755595, 2021). "In cohort 1, there was a significant correlation between reduced CDX2 expression and female gender (p = 0.0338); more advanced pT classification (p = 0.0068), lymph node metastasis (p = 0.0167), and distant metastasis (p = 0.0123); and higher tumor grade (p = 0.0163)." (PMID 30257705, 2018). "Therefore, only 235 patients and tumours were available for CDX2 assessment." (PMID 30511046, 2018).
tumor (continued). "Interestingly, notwithstanding the data above showing that the ANXA10 protein was strongly expressed in human serrated morphology CRC and mouse Cdx2−/− BrafV600E serrated tumor epithelium, it was still a surprise that Anxa10 was the top activated gene in the Cdx2−/− BrafV600E-mutant epithelium." (PMID 28072391, 2017). "In addition, the protein expression of MMP-2 was significantly reduced, suggesting that CDX2 suppressed the invasion and metastasis of tumor cells, possibly by downregulating the expression of MMP-2, which was also demonstrated in the results of our previous in vitro investigation." (PMID 26005051, 2015). "In addition, a previous biological study demonstrated that CDX2 may be important in gastric tumorigenesis, whereas another study suggested that CDX2 is a tumor suppressor." (PMID 25738600, 2015). "Thus, we explored the possibility that the paradoxical tumor suppressor and oncogenic phenotypes induced by CDX2 might reflect the generation of a previously unknown homeodomain-less variant." (PMID 25101906, 2014). "Therefore, CDX2 acts as a tumor suppressor in the upper gastrointestinal tract." (PMID 23408490, 2013). "In addition, a negative correlation was observed between CDX2 expression and the depth of tumor invasion and lymph node metastasis, suggesting that CDX2 may serve as a powerful predictor for GC." (PMID 23408490, 2013). "Based on our results, CDX2 transcriptional factor might act as a tumour suppressor." (PMID 24228025, 2013). "Despite the fact that CDX2 reactivity could be detected in small number of other non-GI tract epithelial tumors, it has been used as a diagnostic marker for tumor of GI tract origin in surgical pathology practice." (PMID 22848863, 2012). "IHC markers showed varying positivity rates across different tumor types, with GATA-3, CDX2, and TTF1 proving particularly useful in distinguishing the tumor origin." (PMID 40751531, 2025). "Immunohistochemistry of the tumor cells revealed positivity for MUC5AC and MUC6 and negativity for MUC2 and CDX2." (PMID 41256328, 2025). "The higher prevalence of the mucinous histological subtype, poor tumor differentiation, increased HER2 expression, and reduced CDX2 expression suggest potential molecular pathways driving the aggressive nature of EO-CRC." (PMID 40142201, 2025). "In this study, we found that CDX2 and HTR2B, markers of the CMS2/3 and CMS4 subgroups, respectively, are present in the same tumor samples." (PMID 41034989, 2025). "In contrast, the fractions of tumor cells positive for the classical markers, MUC5AC and CDX2, were higher in tumorin_lobules compared to tumorin_stroma (adjusted p-values: 1.071e-4 and 2.620e-3, respectively)." (PMID 41006303, 2025). "Immunophenotyping found tumor cells that were CK (+), CD56 (+), Syn (+), EMA (+), β-catenin (membrane +), LCA (−), CD99 (−), S100 (−), HMB-45 (−), SOX-10 (−), TTF-1 (−), CDX-2 (−), and CD34 (−), along with a Ki-67 proliferation index of 60–70%." (PMID 41245381, 2025). "We evaluated the function of CDX2 in CRC proliferation and migration using CRISPR/Cas9 technology and demonstrated a possible link to tumor dissociation and tumor budding." (PMID 40619482, 2025). "Taken together, our results provide further insight into the function of CDX2 in preventing CRC cell migration, tumor budding and tumor aggressiveness." (PMID 40619482, 2025). "We further analyzed the correlations between CDX2/SATB2 expression and immune cell densities separately at the tumor center and at the invasive margin, and the findings were largely similar to those for overall immune cell densities." (PMID 39998677, 2025).
tumor (continued). "The tumor cells exhibited positivity for cytokeratin 7 (CK7) and caudal type homeobox 2 (CDX-2) but negativity for cytokeratin 20 (CK20), paired box 8 (PAX8), NK3 homeobox 1 (NKX3.1), and thyroid transcription factor 1 (TTF-1)." (PMID 39350874, 2024). "Both tumor patterns were immunohistologically positive for CK20, CDX2, and CEA with predominantly equal intensities in the cells of the CC and CV components, respectively, whereas SATB2 was significantly reduced in the clear cells." (PMID 39039246, 2024). "The IF characterization of the PDOs confirmed that the PDO expression of CDX2 and CK20 matched that of the fixed parent tumor tissue." (PMID 38542253, 2024). "Caudal-type homeobox 2 (CDX2) is an intestine-specific transcription factor and it functions as a tumor suppressor." (PMID 38612832, 2024). "Apart from SKP2, ITGB4, CDKN3, TFGP1, SLCO1B3, CDX2 and KIF18A, the remaining model genes showed significant correlations with stem cell score, immune score and tumour microenvironment." (PMID 39656479, 2024). "Given our findings, with a higher frequency of CDX2 than CK20 and especially prevalent GPA33 and CDH17 expression, further studies of this tumor subtype would be of value." (PMID 37349623, 2024). "In contrast, in addition to Clu and Ly6a, the tumor stem cell population of BLM tumors had significant upregulation of differentiation-related genes such as Guca2a, Car1, Cdx2, Car2, and Muc2." (PMID 38893159, 2024). "The role of CDX2 and NDRG1 as putative regulators for BLM tumor cell differentiation was verified using organoids derived from BLM tumors." (PMID 38893159, 2024). "For that, we retrospectively assessed a clinically characterised cohort of mCRC patients from a large comprehensive cancer centre, and chronologically classified the expression of CDX2 and COX2 in tissue microarray (TMA) of mCRC tumour samples." (PMID 38439814, 2024). "Given the detailed insights into tumor heterogeneity provided by cell-type enrichment using DVP, we expanded our proteomics investigation to include CDX2- stromal and CDX2++ epithelial cells across all nine CRA individuals." (PMID 39252972, 2024). "Tumours of the int group usually express cytokeratin-20 (CK20), caudal-type homeodomain transcription factor 2 (CDX2), and mucin-2 (MUC2)." (PMID 37504367, 2023). "Among CDX2, TTF-1 and ISLET-1, which correlate with an intestinal, pulmonary or pancreatic origin of the tumor, the expression of TTF-1 was most frequently determined (67%), followed by CDX2 (58%) and ISLET-1 (35%)." (PMID 37686593, 2023). "In another subset of intestinal‐type ECA cases (5/9, 55.6%), the tumor comprised mucinous epithelium exhibiting an intermediate gastric and intestinal phenotype and diffuse positive CLDN18 (M) and CDX2 expression." (PMID 35861118, 2023). "Meanwhile, the tumor cells were positive for Syn, CD56, CDX2, CEA, Villin, and CK 20, further confirming its dual neuroendocrine and glandular differentiation." (PMID 37083794, 2023). "Expression of CDX2 is higher in epithelial-like tumor (CMS2/3), while expression of HTR2B and FRMD6 is higher in mesenchymal-like tumor (CMS4)." (PMID 37404825, 2023). "Diagnosis of gastrointestinal tract (GIT) tumours requires a different set of biomarkers, the most useful of which include CK20, CDX2, and most recently SATB2." (PMID 35027072, 2022). "Markers CD24, CD44, PDX1, synaptophysin, CD49, CDX2, CD45, DAXX, PCAD and CK7 had lower expression in the tumour relative to that in the non-tumour with the exception of one patient." (PMID 36362433, 2022). "Pathological features that specialists were most unsure of included CDX2 status, EGFR status, Lymph node ratio, KRAS status, BRAF status and tumour budding." (PMID 35323316, 2022).
tumor (continued). "It has been shown to regulate tumor cell growth and metastasis via a variety of downstream target genes, including Selenbp1, EGFR, Foxa2, CDX2, and DDB1." (PMID 36614938, 2022). "The combination of FXR agonist plus EZH2 inhibitor exerts synergistic tumor inhibition in CRC both in vitro and in vivo by dramatically accelerating FXR nuclear location and cooperatively upregulating CDX2 expression." (PMID 35449124, 2022). "Pathological characteristics of organoids including H&E staining and expression of protein markers (CK20, CDX-2, STAB2, CD7, PAX8) were consistent to those of the original tumor." (PMID 35721089, 2022). "Nevertheless, our data showed that PDOs from tumor sites C, E, and F had a moderate expression of both CDX2 and SMAD4, whereas PDOs from tumor sites A, B, and D rarely expressed both proteins." (PMID 35853873, 2022). "Within G2, Ki-67 was lower in Patient 2, and CD24, CDX2 and CD45 were higher in Patient 1 relative to those in the non-tumour tissue, in contrast to the other tissues." (PMID 36362433, 2022). "CD24, CD44, laminin, CD49, CDX2, CK6 and DAXX had lower expression in the tumour relative to that in the non-tumour tissue." (PMID 36362433, 2022). "For example, within Grade 2, relative to that in the non-tumour tissue, the expression of markers CD24, CDX2, CD45 and CK6 was higher in Patient 1, and CD44 was higher in Patient 1 and Patient 3, compared to the other samples in the same group." (PMID 36362433, 2022). "We observe an enrichment for Fra1, Fra2, JunB, Atf3 and AP-1 in tumours with Gleason pattern 3 whereas tumours with Gleason pattern 4 show an enrichment for FOXA1, HOXB13 and CDX2." (PMID 34911933, 2021). "On immunohistochemistry, the tumor cells showed strong cytoplasmic positivity for CK7 and CK20, nuclear positivity for CDX2, and membranous positivity for CEA." (PMID 34307234, 2021). "mRNA levels of Ki-67, CD24, CD44, CD31, MENA, CD49, ECAD, PCAD, EpCAM, CDX2, CK6, CK7, CK13, were significantly decreased in tumour tissue relative to non-tumour tissue." (PMID 33906633, 2021). "Other markers including Ki67, PCNA, DAXX, CD24, CD44, CD31, MENA, Laminin, ECAD, PCAD and CDX2 and CK14 showed different trends in expression between tumour and non-tumour with qRT-PCR compared to IHC." (PMID 33906633, 2021). "We evaluated CDX2 expression in 1003 CRCs and explored its prognostic relevance compared to CRC subtypes, tumour budding and WHO grade in the overall cohort and in specific subgroups." (PMID 34616012, 2021). "Intriguingly, the upregulation of CDX2 by LIN28B inhibited CRC cell invasion in vitro, whereas it promoted metastatic CRC tumor colonization through epithelial-mesenchymal transition (EMT)." (PMID 33755595, 2021). "The three “canonical” intestinal markers CDX2, CK20 and MUC2 were individually expressed by 56%, 54% and 54% of tumours, respectively, with 79% of all cases showing at least one of such markers." (PMID 33963925, 2021). "Interestingly, in pathological situations the context-dependent activity of CDX2 could provide hints to explain opposite effects, being a tumor suppressor in its physiological site of expression, the gut, but an oncogene when ectopically expressed in the hematopoietic lineage." (PMID 34759958, 2021). "Finally, we investigated whether CDX2 contributes to the anti‐tumour potential of NK cells." (PMID 33733587, 2021). "In 45 % (23/51) of the cases more than 70% of the tumor area was stained for CK20, while in 60% (30/50) of the cases similar staining was seen for CDX-2." (PMID 34680393, 2021). "In the present study, we identified nicotine as a stimulator of YAP nuclear localization, which enhanced the expression of YAP target genes (CDX2, CDC20, CTGF, and CYR61) and enhanced tumor growth." (PMID 32894161, 2020). "Immunohistochemical (IHC) tests revealed 100 and 90 percent of the tumor cells to be CDX2 and CK20 positive, respectively, while a moderately high level of tumor cells showed CK7 positivity." (PMID 31026045, 2020).
tumor (continued). "The transcription factor Caudal type Homeobox 2 (CDX2) is crucial for the homeostasis of the colonic epithelium, and has been shown to be at tumour suppressor." (PMID 32408894, 2020). "Of note, although CDX1 and CDX2 were found to be both inactivated and underexpressed, several TFs such as KLF5 or ATOH1 with established tumor suppressor roles in colorectal cancer were only found inactivated via SCIRA." (PMID 33083012, 2020). "In the present case, the tumor cells with mucinous and signet ring cell‐like features were positive for CD20 and CDX2, respectively, indicating enteric differentiation." (PMID 33044008, 2020). "Immunohistochemically, tumor cells were diffusely positive for CK7, MUC6 and CA-IX, but focally positive for CK20 and CDX2." (PMID 31279344, 2019). "Because her tumor's immunophenotypic profile was positive not only for MUC1 and CK7 but also for CK20 and CDX‐2, her tumor was considered ambiguous with both pancreaticobiliary‐type and intestinal‐type features." (PMID 31102323, 2019). "To confirm a direct inhibitory effect of IL-17 on the production of chemokines, we isolated tumor cells from Cdx2-Cre-ERT+/ApcF/F mice, and cultured these cells in Matrigel to form tumor spheres." (PMID 31775909, 2019). "The colonic origin was proved by positivity of tumor cells for CK20 and inconstant positivity for CDX2." (PMID 31205468, 2019). "Of note, the three tumor lesions shared the same immunohistochemical staining pattern, showing negative expression of CK7 and CK20 markers and positive expression of CDX2, MUC1, MUC2, and MUC3." (PMID 31779681, 2019). "CDX2 status (P = 0·018), WHO grade (P = 0·002), tumour budding (P < 0·001), PDC grade (P < 0·001), LVI (P < 0·001), PNI (P < 0·001), EMVI (P < 0·001), type of margin (P = 0·001) and pT category (P = 0·006) were associated with LNM in univariable analysis." (PMID 30511046, 2018). "The average tumor area was significantly reduced in CDX2;APC;PID mice (3 mm2) compared with those found in CDX2;APC mice (14 mm2)." (PMID 30150766, 2018). "Immunohistochemical examination revealed that the tumor cells were positive for CK7 and CDX-2, similar to the cholangiocarcinoma, and negative for thyroid transcription factor-1, napsin A, and CK20." (PMID 29784024, 2018). "To validate our findings regarding CNVs identified by CNVpanelizer, we investigated SOX11, CDX2, MMP9, CARD11 and EDEM2 copy numbers in 41 tumour sections by gene-specific FISH." (PMID 28120820, 2017). "Positive staining of tumor cells for CK20, villin and/or CDX-2 attests for intestinal differentiation." (PMID 28321774, 2017). "The positivity of the tumor for CK7, β-catenin in a membranous/cytoplasmic staining pattern, CDX2, and AMACR, and negativity for CK20, p63, PSA, and PSAP, favored a vesical rather than a colorectal or prostatic origin." (PMID 27006847, 2016). "We further analyzed fresh frozen tumor tissue from 25 CRC patients by RT-PCR for the expression of SOX2 and CDX2." (PMID 27411517, 2016). "Immunohistochemistry revealed that the expression levels of CDX2 and matrix metalloproteinase-2 (MMP-2) were detected in each group, and the protein expression of CDX2 was increased in the tumor tissues from the nude mice in the pEGFP-C1-CDX2 group." (PMID 26005051, 2015). "The tumor was diagnosed as invading the visceral pleura and immunohistochemical staining showed caudal-type homeobox transcription factor 2 (CDX-2)(+), mucin-1(+), cytokeratin 7 (CK7)(+) and thyroid transcription factor-1 (TTF-1)(−) in the tumor cells." (PMID 24348839, 2014). "Immunohistochemical staining showed CDX-2(−), CK20(+), CK7(−) and TTF-1(−) in the tumor cells, confirming metastasis from colorectal adenocarcinoma." (PMID 24348839, 2014). "Immunohistochemical analyses showed that tumor cells stained positive for CD56 (weak), Syn (diffuse), CDX-2 (strong), pan-cytokeratin, cytokeratin 8, cytokeratin CAM5.2 and Ki-67, with the Ki-67 index reaching up to 60%." (PMID 24884973, 2014).